GPR83 (G protein-coupled receptor 83)
Description:
G protein-coupled peptide receptor. Several peptides, PEN, derived from the proSAAS precursor (encoded by PCSK1N), the procholecystokinin-derived peptide proCCK56-63, and the related proteins FAM237A and FAM237B have been reported to activate GPR83 through GNAI1/G(i) and GNAS/G(s)-mediated signaling pathways. However, due to conflicting evidence about the ability of these peptides to bind to and activate the GPR83, the endogenous ligand of GPR83 still remains uncertain. Plays a role in food intake and body weight regulation. May contribute to the regulation of anxiety-related behaviors (By similarity).
Synonyms: GPR72; GIR
Tractability: Small molecule: it belongs to a druggable protein family. Antibody: its Gene Ontology location is reachable by antibodies, with high confidence; UniProt places it where antibodies can reach, with medium confidence; UniProt predicts a signal peptide or a membrane-spanning region.
Target class: Family A G protein-coupled receptor; Membrane receptor
Gene: Protein-coding gene on chromosome 11 (94,377,316 to 94,401,419, reverse strand). Ensembl gene ENSG00000123901.
Subcellular location: Cell membrane
Pathways (Reactome):
Signal Transduction: G alpha (s) signalling events
Gene Ontology:
Molecular function: G protein-coupled receptor activity; neuropeptide receptor activity; neuropeptide Y receptor activity
Biological process: G protein-coupled receptor signaling pathway; neuropeptide signaling pathway; phospholipase C-activating G protein-coupled receptor signaling pathway; feeding behavior
Cellular component: cilium; plasma membrane; membrane; non-motile cilium
Genetic constraint (gnomAD): Loss-of-function variants: 25 observed, 31.47 expected, observed/expected ratio (o/e) 0.79, 90% interval 0.58 to 1.11. The upper end of that interval is the gene's LOEUF score, 1.11, which puts it in group 4 of 6, group 1 being the genes least tolerant of losing a copy. Missense variants: 610 observed, 561.63 expected, observed/expected ratio (o/e) 1.09, 90% interval 1.02 to 1.16. Synonymous variants: 234 observed, 228.01 expected, observed/expected ratio (o/e) 1.03, 90% interval 0.92 to 1.14.
Homologues: Orthologues: chimpanzee GPR83 (99% identical), pig GPR83 (92% identical), rabbit GPR83 (92% identical), dog GPR83 (91% identical), guinea pig GPR83 (90% identical), mouse Gpr83 (89% identical), rat Gpr83 (88% identical), tropical clawed frog gpr83.2 (77% identical), zebrafish gpr83 (52% identical), Caenorhabditis elegans tkr-3 (21% identical). Paralogues in human: NPY2R (28% identical), PRLHR (28% identical), TACR1 (25% identical), TACR3 (24% identical), TACR2 (24% identical), NPY4R (23% identical), NPY4R2 (23% identical), NPY1R (22% identical), GPR19 (21% identical), MTNR1A (19% identical), NPY5R (19% identical), GPR75 (18% identical), and 21 more.
Diseases named in the same sentence as GPR83 in open-access papers:
GPR83 is named in the same sentence as 13 diseases in open-access papers, as found by Europe PMC text mining. Sharing a sentence is not in itself a finding about the gene and the disease. The quoted sentences say what the papers report.
Anxiety (3 papers, 2021 to 2023). Intense feelings of nervousness, tension, or panic often arise in response to interpersonal stresses. "gpr83 (G‐protein coupled receptor 83) encodes a receptor that plays a role in the regulation of energy metabolism, feeding, reward pathway, and stress/anxiety responses in mice." (PMID 37360028, 2023). "The nucleus accumbens is another brain region that contains a high concentration of GPR83 positive cells, and has been strongly implicated in vulnerability and resilience responses to stress as well as anxiety-like behaviors." (PMID 34512237, 2021). "These brain regions play a role in anxiety, display significant GPR83 expression, and form circuits that encode positive and negative affective valence." (PMID 34512237, 2021). "We found that global loss of GPR83 leads to a decrease in anxiety-related behaviors which is more prominent in male compared to female mice." (PMID 34512237, 2021). "Because PV+ neurons in the NAc have been specifically implicated in anxiety-like approach behaviors, we also characterized PV+ and GPR83+ co-expression in the NAc." (PMID 34512237, 2021). "The current studies suggest that removing GPR83 from all these regions may shift the overall output in a direction which favors less anxiety and the mechanisms that underlie this remains to be examined." (PMID 34512237, 2021). "Together, these results show that global loss of GPR83 produces a decrease in anxiety levels." (PMID 34512237, 2021). "GPR83, a recently deorphanized receptor activated by the abundant neuropeptide PEN, has also been identified as a glucocorticoid regulated receptor (and named GIR) suggesting that this receptor may be involved in stress-responses that underlie anxiety." (PMID 34512237, 2021). "Early studies have shown that GPR83 expression is regulated by the glucocorticoid receptor agonist dexamethasone, suggesting a role for GPR83 in stress and anxiety responses, since glucocorticoid release is a hallmark of the stress response." (PMID 34512237, 2021). "G protein-coupled receptor 83 (GPR83) is a class A G protein-coupled receptor with predominant expression in the cerebellum and proposed function in the regulation of food intake and in anxiety-like behavior." (PMID 37894796, 2023). "In contrast, a local GPR83 knockdown in the basolateral amygdala leads to more anxiety-related behaviors in female mice." (PMID 34512237, 2021). "Overall, these data indicate that GPR83 expression in the BLA regulates anxiety levels in female mice however, revealing these differences depends on the sensitivity of the assay used." (PMID 34512237, 2021). "In this study, we investigate anxiety-related behaviors in male and female mice with global knockout and following local GPR83 knockdown in female mice." (PMID 34512237, 2021). "Together, our studies uncover a significant, but divergent role for GPR83 in different brain regions in the regulation of anxiety-related behaviors, which is furthermore dependent on sex." (PMID 34512237, 2021). "A complete study of the effect of estrous cycle on GPR83 and its role in anxiety-related behaviors is warranted due to the potential observed in the current results." (PMID 34512237, 2021). "We observed that global GPR83 KO decreased anxiety-related behaviors in male mice but had limited effects on anxiety-related behaviors in females." (PMID 34512237, 2021). "In our studies, complete removal of GPR83 in the knockout animal produced decreases in anxiety-related behaviors while specific knockdown in the BLA resulted in more anxiety-related behaviors." (PMID 34512237, 2021). "We find that a global knockdown of GPR83 has minimal impact on anxiety-like behaviors in female mice and a decrease in anxiety-related behaviors in male mice." (PMID 34512237, 2021). "Next, we examined the estrus cycle-dependency on anxiety following GPR83 KD in the BLA." (PMID 34512237, 2021). "Consistent with this, GPR83 null mice have been found to be resistant to stress-induced anxiety." (PMID 34512237, 2021).
Anxiety (continued). "Anxiety-related behaviors in GPR83 WT and KO mice were analyzed using the EPM and open field tests." (PMID 34512237, 2021). "The data were further analyzed to determine the extent to which sex differences might contribute to anxiety-related behaviors in the global GPR83 KO mice." (PMID 34512237, 2021). "Furthermore, recent studies demonstrated that suppressing parvalbumin neuron activity in the BLA upregulates anxiety-related behaviors similar to the increases in anxiety seen following GPR83 knockdown in the BLA." (PMID 34512237, 2021). "Since female mice had higher baseline levels of anxiety compared to males, we sought out to determine whether a focused decrease in GPR83 expression in specific brain regions of female mice may induce a greater effect on anxiety-related behaviors." (PMID 34512237, 2021). "Our initial behavioral studies also included both male and female subjects to determine whether GPR83 plays a differential role in anxiety-related behaviors between the two sexes." (PMID 34512237, 2021). "Furthermore, regional changes in expression of GPR83 significantly impacts the overall tone of anxiety-related circuitry, and specifically, GPR83 expression in the BLA may be a primary output node for regulating anxiety-related behavior." (PMID 34512237, 2021). "Overall, these data indicate that lack of GPR83 produces a decrease in anxiety-related behaviors that is more pronounced in male mice, likely due to their higher levels of baseline anxiety compared to female mice." (PMID 34512237, 2021). "G protein-coupled receptor 83 (GPR83), also termed glucocorticoid-induced receptor (GIR), GPR72, KIAA1540, or JP05, is a class A G protein-coupled receptor with predominant expression in the cerebellum and proposed function in the regulation of food intake and in anxiety-like behavior." (PMID 37894796, 2023). "Another important finding of this study is that knockdown of GPR83 in the BLA of female mice increased anxiety-related behaviors in the EPM test irrespective of whether the animals were in the estrus or diestrus stage." (PMID 34512237, 2021). "We find that local GPR83 KD in the BLA resulted in a decrease in the amount of time spent (unpaired t-test, t = 5.223, df = 23, ∗∗∗p < 0.001) and frequency to enter (unpaired t-test, t = 3.119, df = 22, ∗∗p < 0.01) the open arm of the EPM indicating an increase in anxiety-related behaviors." (PMID 34512237, 2021). "In agreement with other studies, we found that female wild-type mice tend to display lower baseline levels of anxiety; this could account for the lack of effect of the global GPR83 KO on anxiety-related behaviors in female mice." (PMID 34512237, 2021). "In fact, studies have reported that mice lacking GPR83 are resistant to stress-induced anxiety." (PMID 34512237, 2021). "Finally, a study examining behaviors of mice lacking GPR83 noted that they were resilient to stress-induced anxiety." (PMID 34512237, 2021).
Obesity (3 papers, 2014 to 2022). Accumulation of substantial excess body fat. "Gpr83 knock-out mice are protected from diet-induced obesity." (PMID 25516095, 2014). "However, Gpr83−/− mice were protected from diet-induced obesity and glucose intolerance, and plasma levels of acyl-ghrelin and des-acyl-ghrelin were unaffected when fed a high-fat diet for 18 weeks, indicating that GPR83 likely has ghrelin-independent roles in appetite regulation." (PMID 34663757, 2021).
thymoma (2 papers, 2012 to 2024). A neoplasm arising from the epithelial cells of the thymus. "GPR83, also known as JP05, GIR, and GPR72, is a GPCR initially identified in thymoma as a glucocorticoid-induced receptor." (PMID 38895631, 2024).
autism (1 paper, 2016). Persistent deficits in social interaction and communication and interaction as well as a markedly restricted repertoire of activity and interest as well as repetitive patterns of behavior. "Three types of CvN unique genes were registered in the autism KB database: Cadm3 (cell adhesion molecule), Gpr83 (G protein-coupled receptor), and Acta1 (actin α1)." (PMID 27782041, 2016).
colitis (1 paper, 2008). Inflammation of the colon. "Using a T-cell transfer model of colitis we found that CD4+ CD25+ TR cells from Gpr83-deficient mice were able to suppress the development of colitis induced by wild-type or Gpr83−/− CD45RBhi naïve CD4+ T cells." (PMID 18479351, 2008). "Gpr83 expression was dispensable for the regulatory activity of nTR cells as Gpr83-deficient nTR cells could suppress the development of disease in a T-cell transfer model of colitis." (PMID 18479351, 2008). "Thus Gpr83-deficient mice had normal frequencies of CD4+ Foxp3+ cells in the primary and secondary lymphoid organs and these cells retained their suppressive activity in vivo in a T-cell transfer model of colitis." (PMID 18479351, 2008). "Furthermore, there was no histological evidence of colitis (data not shown), indicating that Gpr83 is not crucial for the maintenance of intestinal homeostasis or the effective functioning of nTR cells within the colon or associated lymph nodes." (PMID 18479351, 2008).
cancer (1 paper, 2020). A tumor composed of atypical neoplastic, often pleomorphic cells that invade other tissues. "Many proteins belong to these families are closely related to cancers, which means ‘CEP72’, ‘CEP131’ and ‘GPR83’ might be predicted as being TC-associated in the future." (PMID 32164526, 2020).
infection (1 paper, 2023). The state of being infected such as from the introduction of a foreign agent such as serum, vaccine, antigenic substance or organism. "After infection, the Lag3hi Treg and Gpr83+Igfbp4+ naive Treg subpopulations were specifically induced in PBMCs and the spleen, respectively." (PMID 37039643, 2023). "Meanwhile, we observed that Treg subpopulation 6 was naive Treg cells, increased after infection, and specifically expressed Gpr83 and Igfbp4." (PMID 37039643, 2023). "Additionally, Treg cell subpopulation six was substantially increased in PBMCs and spleens of mice after infection, and its specific highly expressed genes Gpr83 and Igfbp4 have the potential to become biomarkers for the diagnosis and prognosis of CE." (PMID 37039643, 2023).
GPR83 also shares sentences with these, for which no sentence is quoted: glioma (2 papers); Glucose intolerance (2); CNS tumors (1); Hearing impairment (1); osteosarcoma (1); Splenomegaly (1).